FABP4 (fatty acid binding protein 4)
Diseases named in the same sentence as FABP4 in open-access papers (continued):
Sharing a sentence is not in itself a finding about the gene and the disease.
metabolic disease (continued). "Inhibiting FABP4 is a viable and appealing therapeutic opportunity for treating metabolic disorders." (PMID 36985701, 2023). "FABP4 acts as a lipid chaperone to take up lipids and fatty acids under pathophysiological conditions and can be a therapeutic target for metabolic disorders." (PMID 36339572, 2022). "Of particular note, several studies have reported that adipocyte-derived FABP4 in the setting of metabolic disorders acts as a paracrine-endocrine signaling agent in the development and/or progression of vascular disease." (PMID 36358315, 2022). "The role of FABP4 in cardiovascular and metabolic diseases has been widely investigated and some achievements have been made." (PMID 36060264, 2022). "Small molecule specific FABP4 inhibitors and/or FABP4 neutralizing antibodies can be novel therapeutic strategies against metabolic disorders and vascular remodeling." (PMID 33071982, 2020). "Adipocyte fatty acid–binding protein (FABP4) is an adipokine that plays an important role in development of cardiovascular and metabolic diseases." (PMID 32075656, 2020). "It was only with the use of Ab therapies, however, that hormonal FABP4 was clearly identified as having a robust role in metabolic diseases, as Abs cannot enter cells and cannot pass the blood-brain barrier to act within the CNS." (PMID 30705117, 2019). "The potential treatment of metabolic disease by targeting circulating FABP4 concentration has been recently proposed; therefore, there is increasing interest in circulating FABP4 concentration as a disease biomarker." (PMID 31826012, 2019). "Our results suggest that higher expression of FABP4 in BAs is one of the key factors in these metabolic disorders." (PMID 30453990, 2018). "Of note, in our study the adiponectin adipose tissue expression appeared as a positive determinant of FABP4 expression, a protein with a predominant role in insulin sensitivity with probable anti-inflammatory activity in metabolic diseases." (PMID 23139800, 2012). "Furthermore, our study represents a substantial stride in advancing our understanding of the potential significance of FABP4 in metabolic disorders, highlighting its promising role as a biomarker for cardiometabolic derangement." (PMID 38731797, 2024). "Given the strong link between hormonal FABP4 and a multitude of chronic and metabolic diseases in both mice and humans, it is possible that there are different functional roles for FABP4 depending on the cellular source and the lipid environment in the biological functions of this hormone." (PMID 37172691, 2023). "It has recently been suggested that manipulation of FABP4 by using neutralizing antibodies, specific inhibitors or unidentified receptor blockers would be a novel therapeutic strategy for several cardiovascular and metabolic diseases." (PMID 33071982, 2020). "A further understanding of the mechanisms by which FABP4 level is changed by pharmacological modulation may enable the development of new therapeutic strategies for cardiovascular and metabolic diseases." (PMID 32539832, 2020). "Since plasma-circulating FABP4 has the potential to modulate the function of several types of cells, it appears to be of extreme interest to try to develop potential therapeutic strategies targeting the pathogenesis of metabolic diseases in this respect." (PMID 30857223, 2019). "In proinflammatory M1 macrophages that accumulate in adipose tissue during obesity-linked metabolic diseases, UCP2 expression is blocked by adipocyte FA binding protein (FABP4/aP2), and the resulting release of redox signaling is involved in inflammasome activation and IL-1β secretion." (PMID 29351723, 2018). "Furthermore, a recent study demonstrated the possibility of a new strategy to treat metabolic disease by targeting serum FABP4 with a monoclonal antibody to FABP4." (PMID 27936164, 2016).
metabolic disease (continued). "One explanation may be that both FABP4 and adiponectin can be produced and released from adipocytes and are related to inflammation and metabolic disorders." (PMID 26823558, 2016). "Viewing the FABP4 mRNA down-regulation found in obese patients, we are tempted to speculate about a possible adipose tissue dysfunction leading to metabolic disorders." (PMID 23139800, 2012). "Furthermore, FABP4 can be secreted into various bodily fluids such as plasma and, in fact, significant increases in the serum levels of FABP4 have been detected in patients with cardiovascular and metabolic diseases." (PMID 39062961, 2024). "Notably, circulating FABP4 level serves as a potential biomarker for these metabolic disorders." (PMID 35899119, 2022). "FABP4 is a fatty acid-binding protein, which has been related to the occurrence and progression of chronic metabolic diseases and may directly affect drug discovery in metabolic diseases." (PMID 36532833, 2022). "The key role of FABP4 in regulating systemic metabolism could also be evidenced by various biochemical and genetic studies demonstrating an important role for FABP4 levels in metabolic diseases." (PMID 34676825, 2021). "This exciting development allows us to understand the contribution of serum FABP4 to metabolic diseases in the context of peripheral tissues and develop a greater understanding of how targeting circulating FABP4 may be used clinically for the prevention or treatment of immunometabolic diseases." (PMID 30705117, 2019). "A further understanding of the mechanisms of FABP4 expression in and secretion from adipocytes and their pharmacological modulation may enable development of new therapeutic strategies for cardiovascular and metabolic diseases." (PMID 27124282, 2016). "To determine the effects of gut microbiota on the expression of FABP4, adipsin and adiponectin in gut epithelial Paneth cells, we first employed the germ-free (GF) mice, which are often used as a model to explore the effect of gut microbiota on the metabolic diseases." (PMID 26687459, 2015). "Together, the study reveals the regulatory mechanisms of KDM5A in age-dependent metabolic disorders and identifies KDM5A/FABP4 axis as a potential therapeutic target for vascular aging and related organ dysfunction." (PMID 41236095, 2025). "Consequently, an increase in the FABP4 levels may indicate the presence of metabolic disorders." (PMID 38139788, 2023). "In addition, FABP4 could be a potential target for treating metabolic diseases." (PMID 23139800, 2012). "FABP4 and FABP5 in adipocytes and macrophages contribute to inflammatory and metabolic disorders." (PMID 37794302, 2024). "The downregulation of FABP4 upon LCM treatment suggests a potential dual benefit of LCM in both reducing lipid accumulation and modulating inflammatory responses, which are often interconnected in metabolic disorders." (PMID 39201257, 2024). "A further investigation of the mechanism of integrated actions of FABP4 and FABP5 may enable the development of new therapeutic strategies for metabolic disease and atherosclerotic cardiovascular disease." (PMID 33071982, 2020).
infection (25 papers, 2012 to 2026). The state of being infected such as from the introduction of a foreign agent such as serum, vaccine, antigenic substance or organism. "We also demonstrate that FABP4 inhibitor treatment of infected Syrian hamsters decreased viral loads and alleviated the infection-associated immunopathology." (PMID 39843629, 2025). "Indeed, when examining the co-localization scores over time, we found that FABP4’s association with dsRNA and calnexin occurred as early as 8 h post infection, and peaked at 12 to 24 h." (PMID 39843629, 2025). "By comparing the transcriptomic profiles of infected cells, bystander cells, and unexposed cells, we identified precise modulation of several key pathways: first, the "Fabp4/Cd36 lipid metabolism pathway" is activated during early infection." (PMID 41827050, 2026). "To contextualize the role of intracellular FABP4 during infection, we examined its protein abundance and RNA expression but found no changes across the samples collect 24 and 48 h after infection (Fig. EV2E–G)." (PMID 39843629, 2025). "We then measured FABP4 secretion at 12, 24, and 48 h post infection by incubating the cells with a fresh low-volume media for 1 h at each of the indicated time points." (PMID 39843629, 2025). "We examined common cold coronavirus (HCoV-OC43) infection using a Real-Time Cell Electronic Sensing assay (RTCES) to measure cell viability and cytopathic effects (CPE) in wild type and FABP4-deficient mouse pre-adipocytes." (PMID 39843629, 2025). "Infected HBE cells (MOI:1) were treated with the FABP4 inhibitor (CRE-14) then fixed 48 h post-infection." (PMID 39843629, 2025). "Following infection, cells were treated with two doses of both FABP4 inhibitors, and their viral titers were monitored over four days." (PMID 39843629, 2025). "Compared to uninfected cells, FABP4 secretion from infected cells was marginally reduced within the first 12 h post infection (Fig. EV2H)." (PMID 39843629, 2025). "In particular, IFN-λ inoculation markedly elevated Fabp4 and Slamf9 transcriptions in the lungs of CoV2+ hamsters from an early stage of infection." (PMID 36524125, 2022). "FABP4 contributes to promoting inflammation via LDs, which should be considered a new target for drug development to treat infections." (PMID 36371263, 2022). "Fatty-acid binding protein 4 (FABP4) is an adipokine involved in the innate immune response against infection produced by alveolar macrophages (Mɸ)." (PMID 31931795, 2020). "Compared to mock-infected cells at day 1 post-infection, C. burnetii infection upregulated the expression of genes acat-1, acat-2, fabp-4 and apoE by more than 1.2 fold." (PMID 29390006, 2018). "In addition, FABP4 inhibition significantly decreased IL-6 secretion 48 h post-infection, suggesting an improved inflammatory state." (PMID 39843629, 2025). "Notably, both patterns were observed in cells neighboring nucleocapsid positive cells, suggesting a dynamic change in FABP4 distribution at different stages of infection." (PMID 39843629, 2025). "qRT‐PCR analysis revealed that lenti‐shPPARGC1B infection significantly decreased PPARGC1B mRNA expression, which resulted in significant down‐regulation of the mRNA levels of the adipogenic differentiation markers (PPARγ, PLIN1, LPL and FABP4) as compared with the lenti‐ctrl infection." (PMID 29993187, 2018). "In addition, VBNC-BMDM infection up-regulated Fabp1 and Fabp2 and down-regulated Fabp4." (PMID 39714095, 2025). "We also found that inhibiting FABP4, CPT-1, or FAO eliminates the infection-induced elevation of mitochondrial and cellular reactive oxygen species (ROS) in adipocytes." (PMID 40919813, 2025). "However, the specific role of FABP4 during infection is unknown." (PMID 36371263, 2022). "Infection of these cells confirmed that in the absence of FABP4, nucleocapsid protein abundance and viral titers were significantly reduced." (PMID 39843629, 2025).
infection (continued). "We evaluated the LD content across control and inhibitor-treated cells and found that FABP4 inhibition did not affect LDs in uninfected cells or prevent their hydrolysis during infection (Fig. EV3N)." (PMID 39843629, 2025). "In this study, we identified several proteins (FABP4, LEP, RARRES2, MSTN, C2, SELE and IL6) that belong to a family of chronic pro-inflammatory cytokines and are primarily produced in response to infection or stress, some of which are mainly produced by adipose tissue (FABP4, LEP and RARRES2)." (PMID 38548792, 2024). "The RNA levels of adipogenic genes leptin and FABP4 exhibited no significant changes, while Acrp30 expression declined following infection." (PMID 39467689, 2024). "The levels of adiponectin were reduced (p<0.05), FABP4 levels were increased (p<0.01) and PPARγ levels were not changed during infection compared to the levels in control mice." (PMID 33826636, 2021). "In support of this interpretation is the fact that FABP4 facilitates the interaction between Mɸ and neutrophils through the regulation of CXCL1, a chemokine secreted by Mɸ to recruit neutrophils to the site of infection." (PMID 31931795, 2020). "FABP4 is a member of the FABP family of small-molecular weight intracellular lipid chaperones that functions as a secreted adipokine and plays a role in airway defense against infection." (PMID 31931795, 2020). "Moreover, infection with the cag PAI mutant H. pylori strain resulted in upregulation of gastric PPAR γ responsive genes (i.e., CD36 and FABP4), suggesting increased PPAR γ activation in vivo." (PMID 23166823, 2012). "However, in the isolated cultured adipocytes, we did not detect an increase in FABP4 secretion upon infection." (PMID 39843629, 2025). "The mRNA levels of PPAR target genes associated with adipocyte differentiation, including ADRP, FABP4, CD36, APOE, APOC1, ASCL1, were strongly induced in THP-1 cells at 6 or/and 48 h after infection by M. leprae but not stimulation by dead M. leprae, as showed by real-time PCR." (PMID 33075048, 2020). "qRT‐PCR analysis revealed that lenti‐shZFP36L1 infection remarkably decreased ZFP36L1 mRNA expression which resulted in significant up‐regulation of the mRNA levels of the adipogenic differentiation markers (PPARγ, PLIN1, LPL and FABP4) as compared with the lenti‐control (lenti‐ctrl) infection." (PMID 29993187, 2018). "Although we expected FABP4 to play a role in promoting DNL during infection, its inhibition did not alter LD content or prevent infection-induced LD hydrolysis." (PMID 39843629, 2025). "In colon, none of these proteins or pathways has been altered, but FABP4, other protein belonging to the FABP family, has result overexpressed after the infection." (PMID 26389078, 2015).
inflammation (5 papers, 2012 to 2025). Aberrant reaction of the microcirculation characterized by movement of fluid and leukocytes from the blood into extravascular tissues. "Increased FABP4 in pulmonary epithelial and endothelial cells drives immunopathology in various models of airway inflammation, and its inhibition or genetic deletion reduces proinflammatory cytokines, immune cell recruitment, and improves airway function." (PMID 39843629, 2025). "We demonstrated that FABP4-Cre-BMPR2fl/fl (CKO) mice presented with spontaneous lung inflammation and significantly increased lung injury score, in comparison with WT mice." (PMID 37886639, 2023). "The lipid transporter FABP4 is a potential mediator of inflammatory responses that has been suggested to play a crucial role in mediating renal inflammation and fibrosis in HN." (PMID 35153751, 2021).
neurodegenerative disease (4 papers, 2023 to 2025). A disorder of the central nervous system characterized by gradual and progressive loss of neural tissue and neurologic function. "Therefore, identification of more drug-like FABP4 chemical inhibitors are required, which may then be used to alleviate microglia-induced neuroinflammation in many neurodegenerative diseases, such as AD, PD and MND." (PMID 37555918, 2023). "IF regulates lipid metabolism primarily via genes including FABP4, WNT10B, PCK1, PLIN1, LEPR, and ADIPOQ, providing energy for cold adaptation, whereas PF positively influences in vivo degenerative diseases mainly through genes such as ATP5F1A, ATP5PO, SDHB, NDUFS8, SDHA, and COX5A." (PMID 40136641, 2025). "Fatty acid-binding protein 4 (FABP4) is a key lipid binding protein expressed in microglia, which has been demonstrated to play a critical role in microglial-mediated neuroinflammation, a component of many neurodegenerative diseases." (PMID 40234265, 2025). "Fabp4 is also part of the PPAR signaling pathway and may mitigate mitochondrial dysfunction by reversing excessive fatty acid oxidation or correcting mitochondrial defects in neurodegenerative diseases." (PMID 41294802, 2025).
retinopathy (4 papers, 2014 to 2025). "In a previous study, the abnormally upregulated expression of FABP4 was observed in retinopathy, and FABP4 deficiency thus improves pathological retinal vascularization, suggesting a possible protection against retinopathy." (PMID 40076418, 2025). "Collectively, our findings suggest FABP4 as a potential target of pathologic retinal angiogenesis in proliferative retinopathies." (PMID 24802082, 2014).
bacterial infections (3 papers, 2013 to 2025). "FABP4’s consistent performance across cohorts with differing microbiology–predominantly bacterial infections in adults and viral in children–suggested that FABP4 is agnostic to the type of pathogen causing LRTI8." (PMID 41402257, 2025).
cardiac disease (3 papers, 2014 to 2022). "Subsequently, FABP4 has been linked to structural heart disease and contractile dysfunction by modulating calcium dynamics in cardiomyocytes." (PMID 36232410, 2022). "Whether FABP4 can serve as a biomarker for early diagnosis of high-risk individuals with heart disease and a potential therapeutic target for cardiac dysfunction warrants further investigation." (PMID 25142635, 2014).
Gastrointestinal tumors (2 papers, 2020 to 2022). "FABP4 can be used as a diagnostic and prognostic biomarker in pancancer, and its high expression in gastrointestinal tumors suggests poor prognosis." (PMID 36532833, 2022). "We found that FABP4 expression in gastrointestinal tumors was more correlated with M2 macrophages and DC cells." (PMID 36532833, 2022). "The low-expression group has a better prognosis than the high-expression group, and the expression of FABP4 in the early T and N stages of gastrointestinal tumors is lower." (PMID 36532833, 2022). "Gastrointestinal tumors with high expression of FABP4 may have more immunosuppressive effects on macrophages and have a worse prognosis." (PMID 36532833, 2022).
immune diseases (2 papers, 2018 to 2025). "This hypothesis suggests that immune dysfunction associated with FABP4, CDR2, and FSTL3 may play a crucial role in the co-morbid development of T2DM and CRC." (PMID 40595026, 2025). "CPT-1, FABP4 are also key targets for the treatment of metabolic and immune diseases." (PMID 30519272, 2018).
hematological cancers (1 paper, 2022). "In addition, some proteins such as the fatty acid-binding protein 4 (FABP4) and nucleolin were also found to regulate DNMT1 levels in hematological cancers." (PMID 36059621, 2022).
FABP4 also shares sentences with these, for which no sentence is quoted: end-stage renal disease (6 papers); bladder tumors (5); prostate (5); renal failure (5); Impaired glucose tolerance (4); squamous cell carcinoma (4); coronary artery stenosis (3); dyslipidaemia (3); Genetic obesity (3); hypertriglyceridemia (3); Left ventricular diastolic dysfunction (3); multiple sclerosis (3); proliferative diabetic retinopathy (3); adenocarcinoma (2); Alzheimer disease (2); anaplastic meningioma (2); arteriosclerosis (2); Autoimmunity (2); benign tumors (2); cardiac arrhythmia (2); cardiomyopathy (2); cholestasis (2); Cushing syndrome (2); End Stage Liver Disease (2); myocardial ischemia (2); nonalcoholic fatty liver (2); pancreatic ductal adenocarcinoma (2); prostate adenocarcinoma (2); rectal adenocarcinoma (2); rectal cancer (2).
A further 91 diseases each share a sentence with FABP4 in 2 papers or fewer.